GAD2 (glutamate decarboxylase 2)
Description:
Catalyzes the production of GABA.
Synonyms: GAD65
Tractability: Small molecule: a structure with a bound ligand is known; it has a high-quality binding pocket. Antibody: UniProt places it where antibodies can reach, with high confidence; its Gene Ontology location is reachable by antibodies, with high confidence. PROTAC: its protein half-life has been measured.
Target class: Enzyme; Lyase
Gene: Protein-coding gene on chromosome 10 (26,216,665 to 26,304,558, forward strand). Ensembl gene ENSG00000136750.
Subcellular location: Cytoplasm, cytosol; Cytoplasmic vesicle; Presynaptic cell membrane; Golgi apparatus membrane
Pathways (Reactome):
Neuronal System: GABA synthesis; GABA synthesis, release, reuptake and degradation
Gene Ontology:
Molecular function: protein binding; glutamate decarboxylase activity; carbon-carbon lyase activity; carboxy-lyase activity; pyridoxal phosphate binding
Biological process: chemical synaptic transmission; gamma-aminobutyrate shunt; gamma-aminobutyric acid biosynthetic process
Cellular component: clathrin-sculpted gamma-aminobutyric acid transport vesicle membrane; cytoplasm; plasma membrane; axon; cytoplasmic vesicle; cytosol; Golgi membrane; presynaptic membrane; synapse
Genetic constraint (gnomAD): Loss-of-function variants: 15 observed, 59.16 expected, observed/expected ratio (o/e) 0.25, 90% interval 0.17 to 0.39. The upper end of that interval is the gene's LOEUF score, 0.39, which puts it in group 1 of 6, group 1 being the genes least tolerant of losing a copy. Missense variants: 503 observed, 609.6 expected, observed/expected ratio (o/e) 0.83, 90% interval 0.77 to 0.89. Synonymous variants: 222 observed, 221.45 expected, observed/expected ratio (o/e) 1, 90% interval 0.9 to 1.12.
Homologues: Orthologues: chimpanzee GAD2 (99% identical), macaque GAD2 (99% identical), dog GAD2 (97% identical), pig GAD2 (96% identical), rabbit GAD2 (96% identical), mouse Gad2 (96% identical), guinea pig GAD2 (94% identical), rat Apbb1ip (90% identical), tropical clawed frog gad2 (84% identical), zebrafish gad2 (78% identical), Drosophila melanogaster Gad1 (47% identical), Caenorhabditis elegans unc-25 (44% identical), and 2 more. Paralogues in human: GAD1 (65% identical), CSAD (43% identical), GADL1 (42% identical), HDC (19% identical), DDC (19% identical), SGPL1 (17% identical), PDXDC1 (16% identical).
Diseases named in the same sentence as GAD2 in open-access papers:
GAD2 is named in the same sentence as 240 diseases in open-access papers, as found by Europe PMC text mining. Sharing a sentence is not in itself a finding about the gene and the disease. The quoted sentences say what the papers report.
type 1 diabetes (149 papers, 2003 to 2026). "Autoantibodies against GAD1 and GAD2 are elevated in type 1 diabetes mellitus and neurological disorders (see Further reading)." (PMID 29055034, 2017). "A similarly small set of 149 genes that is detectably expressed in beta cells of both species, but robustly and significantly enriched in human beta cells includes Gad2, which is a major auto-antigen in human type 1 diabetes." (PMID 25051960, 2014). "GAD2 (also called GAD65) encodes glutamate decarboxylase 2, is a target for islet cell antibodies in type I diabetes." (PMID 19216786, 2009). "Glutamic acid decarboxylase 65 (GAD65; Gad2), one of the two mammalian enzymes that synthesize GABA from glutamate (the other being GAD67, Gad1), is expressed in human beta cells, and is a major autoantigen in type 1 diabetes (T1D)." (PMID 36246925, 2022).
diabetes (121 papers, 2003 to 2026). "This was exemplified by a case study of the involvement of miR-181 and diabetes mellitus, which revealed glutamate decarboxylase 2 and sirtuin-1 as likely causal molecular links between the miRNA and the disease." (PMID 24273243, 2014). "In particular, diabetes has been validated as a prognostic factor in stages I to III colorectal cancer patients, in which GAD2 involved could induce β-cell death." (PMID 32528533, 2020).
Anxiety (60 papers, 2011 to 2026). Intense feelings of nervousness, tension, or panic often arise in response to interpersonal stresses. "A single-nucleotide polymorphism (SNP) variant of GAD2 was also identified as posing a risk for developing anxiety." (PMID 40725163, 2025). "It exhibited a positive relationship with all anxiety symptoms and was tightly associated with GAD2 (Uncontrollable worry), GAD5 (Restlessness), and GAD7 (Feeling afraid)." (PMID 36408014, 2022). "Patients with non-curative treatment prognoses (M = 2.64, SD = 1.51, n = 579) showed higher anxiety levels than those with curative prognoses (M = 2.32, SD = 1.47, n = 398), GAD-2: t = − 3.231, p < .001, d = 0.21." (PMID 41530333, 2026). "Among all anxiety symptoms in the network, GAD2 (inability to stop or control worrying) exhibited the highest strength, followed by GAD3 (worrying too much about various things) (eFigure 1)." (PMID 40420022, 2025). "We subsequently injected AAV‐DIO‐ChR2‐mCherry virus and implanted optical fibers into the ACC of GAD2‐Cre mice, which led to a similar reduction in anxiety‐like behaviors upon photostimulation of ChR2‐expressing ACCGABA terminals in the ACC." (PMID 39487959, 2025). "Network analysis identified CESD3 (Feeling blue/depressed), GAD4 (Trouble relaxing), and GAD2 (Uncontrollable worry) as the most influential central symptoms in the network of depression and anxiety." (PMID 38562253, 2024). "The two symptoms with the strongest correlation in the network of anxiety symptoms were GAD1 (Nervousness or anxiety) and GAD2 (Uncontrollable worry), followed by GAD5 (Restlessness) and GAD6 (Irritability)." (PMID 38562253, 2024). "CESD3 (Feeling blue/depressed) had the highest expected influence, while GAD4 (Trouble relaxing) and GAD2 (Uncontrollable worry) were also statistically stronger than most other nodes in the depression and anxiety network." (PMID 38562253, 2024). "In contrast, Tcf4STOP/+::Gad2-Cre and Tcf4STOP/+ mice exhibited reduced closed arm activity compared to controls, indicating persistence of the reduced anxiety-like phenotype despite reinstatement of Tcf4 in GABAergic neurons." (PMID 35535852, 2022). "The mechanism by which the GABA‐producing system contributes to anxiety and fear has been studied primarily in Gad2 knockout (KO) mice." (PMID 33325157, 2021). "Consistent with these clinical findings, Gad2 KO mice exhibit increased anxiety‐like behavior and enhanced active defensive behavior during the fear‐conditioning test." (PMID 33325157, 2021). "We conducted TWAS by integrating GAD2-GWAS summary statistics of anxiety and two sets of brain gene expression reference panels (i.e., eQTL data) from PsychENCODE and GTEx." (PMID 34650599, 2021). "In our secondary analyses, comparing PwMS/anxiety to healthy controls, we found a 1‐SD GAD‐2 PGS increase was associated with similar odds of comorbid moderate anxiety to that of the primary (OR per 1‐SD increase in GAD‐2 PGS: 1.45, 95% CI: 1.05–1.98)." (PMID 38715244, 2024). "Interestingly, some of the linear dose-response DEGs have been implicated in transmission and plasticity (GRIN2A, GAD2), depression and antidepressant effect (DDIT4, GAD2) anxiety and stress responses (ADCYAP1R1), WNT signalling (FRZB), neurogenesis (ARHGEF39) and hippocampal volume (ANKRD37)." (PMID 39055655, 2024). "Disrupted GABA signaling and GABA deficit is also hypothesized to play a role in the development of depression and anxiety, while Gad2 mRNA, the synthesis enzyme of GABA, was upregulated after chronic treatment with the serotonin and noradrenaline reuptake inhibitor venlafaxine." (PMID 31024264, 2019). "Symptom network analysis reveals a shift in centrality patterns: while depressive symptoms were dominant at T1, anxiety symptoms—particularly GAD3 (Excessive Worry), GAD2 (Uncontrollable Worry), and GAD1 (Nervousness), became more central at T2." (PMID 40893605, 2025).
Anxiety (continued). "Anxiety symptoms (particularly GAD3, GAD2, and GAD1) became more central, while suicidal ideation shifted from a depression-specific cluster to one integrating anxiety symptoms." (PMID 40893605, 2025). "At T2, the symptoms with the highest strength centrality indices were GAD3 (Excessive Worry) (1.53), GAD2 (Uncontrollable Worry) (1.08), and GAD1 (Nervousness) (1.05), indicating a more prominent role for anxiety symptoms in the organization of the network." (PMID 40893605, 2025). "Among the strongest associations, robust links were observed between GAD1 (Nervousness) and GAD2 (Uncontrollable), as well as between GAD3 (Excessive Worry) and GAD4 (Trouble Relaxing), indicating strong interrelations among anxiety symptoms." (PMID 40893605, 2025). "Within the depression and anxiety network, CESD3 (Feeling blue/depressed), GAD4 (Trouble relaxing), and GAD2 (Uncontrollable worry) emerged as the most influential and central symptoms." (PMID 38562253, 2024). "To evaluate the function of vlPAG-DRGABA+ neurons on nociception and anxiety-like behaviors, we designed an experimental timeline and applied an AAV carrying Cre-dependent hM3Dq/hM4Di or mCherry in the vlPAG-DR of GAD2-ires-Cre mice." (PMID 36526697, 2023). "In this study, GAD2 (excessive worrying) emerged as the most central node in the network, whereas a previous study found GAD4 (trouble relaxing) to have the highest centrality value in the network of loneliness, depression, and anxiety symptoms in adults." (PMID 40034186, 2025). "The difference in AUC between pre-treatment screening data and weekly treatment data was significant for the GAD-2 [D = −2.35, p = 0.002], indicating that the GAD-2 had greater discriminative ability for anxiety in the weekly treatment measurements than during pre-treatment screening." (PMID 38800678, 2024). "Meanwhile, among the anxiety symptom community, node GAD3 (“Worry too much”) had the most direct connection with node GAD4 (“Relaxing Trouble”), followed by the connection between nodes GAD1 (“Nervousness”) and GAD2 (“Uncontrollable Worrying”)." (PMID 38026317, 2023). "Students’ grades at the bottom 27% (poor academic group) of 16 nodes demonstrated that 73 out of 120 edges were non-zero, and the edge of GAD-1 (nervousness) and GAD-2 (uncontrolled worry) showed the strongest connection in the anxiety symptoms." (PMID 36925600, 2023). "Further, pharmacogenetic activation of the vLSGAD2 neurons aggravated anxiety of the stressed GAD2-Cre mice but did not alter the basal anxiety level of the naïve ones." (PMID 36614104, 2022). "Meanwhile, pharmacogenetic activation of the vLSGAD2 neurons aggravated anxiety of the stressed GAD2-Cre mice but did not alter the basal anxiety level of the naïve ones." (PMID 36614104, 2022). "Of these 1611 individuals, 756 (46.9%) experienced a decrease in anxiety symptoms as measured by a change from a positive to a negative GAD-2 screen." (PMID 33496679, 2021). "This shift was accompanied by stronger links with anxiety-related symptoms such as GAD1(Nervousness) and GAD2 (Uncontrollable Worry), suggesting that suicidal ideation may increasingly align with an anxiety-based symptom profile rather than with classical depression." (PMID 40893605, 2025). "GAD2 (Being unable to stop or control worrying) and GAD4 (Feeling tense and having difficulty relaxing) were both significant core symptoms in both groups, reflecting the widespread uncertainty and anxiety among the elderly in coping with stressors such as aging, illness, and widowhood." (PMID 40809861, 2025). "Among them, GAD4 “Trouble relaxing” and GAD2 “Uncontrollable worry” had the highest expected influence (EI = 1.15 and 1.14, respectively), and CESD3 “Feeling blue/depressed” was also statistically stronger than most other nodes in the depression and anxiety network (EI =1.07)." (PMID 40502831, 2025).
Anxiety (continued). "Genetic differences in non-dopaminergic neurons (such as Gad2+ neurons), that make up much of our neuron population, have been suggested to contribute to strain specific behavioural differences, including anxiety, reward and motivation traits, such as ethanol consumption." (PMID 34503558, 2021). "Interestingly, pharmacogenetic activation of vLS GAD2 neurons did not alter basal anxiety level compared with the mCherry group in the EPM test, whereas pharmacogenetic activation of vLS GAD2 neurons aggravated anxiety-like behavior in OFT after exposure to the social defeat stress." (PMID 36614104, 2022).
epilepsy (60 papers, 2004 to 2025). A brain disorder characterized by episodes of abnormally increased neuronal discharge resulting in transient episodes of sensory or motor neurological dysfunction, or psychic dysfunction. "With Vglut2:Ndufs4cKO mice, the lethality was associated with severe motor and respiratory alterations, whereas with Gad2:Ndufs4cKO mice, sudden unexpected death was associated with epilepsy (SUDEP) with no overt clinical alteration beyond the weight loss." (PMID 31403401, 2019). "Remarkably, dysregulation of GAD2 has been implicated in neurological disorders such as epilepsy." (PMID 39011116, 2024). "Hence, we hypothesize that basal ganglia inhibitory network is affected in Gad2:Ndufs4cKO mice, being unable to control the activity of cortical excitatory neurons, thus leading to epilepsy." (PMID 31403401, 2019). "Although 5-HT2C receptors are expressed in GABAergic interneurons where various loss-of-function mutations are thought to cause epilepsy by disinhibition, selective expression of the receptors in Gad2+ interneurons was not sufficient to prevent epilepsy or SUDEP." (PMID 34396109, 2021).
depression (35 papers, 2013 to 2025). "Among the proteins mediating the effect of air pollution, nine were associated with Baseline PHQ2, 23 with Incident ICD9/10 Depression, and 38 with Baseline GAD2." (PMID 40611827, 2025). "Another study, consisting of anxiety disorder cases (N = 268), cases with major depression (N = 541), and 541 healthy controls, tested association to 18 SNPs within GAD2." (PMID 23659354, 2013). "Our data show that Chaihu-Shugan-San treats depression potentially via influence 110 DEPs (Gad2, Vamp2, Pde2a, etc.), and neurotransmitters release and transmission cycle (e.g., GABA, glutamate, serotonin, norepinephrine, dopamine, and acetylcholine)." (PMID 35111057, 2021). "One example is shown within the MYO3A gene which lies upstream of GAD2, a primary regulator of GABA synthesis that has been associated with schizophrenia, bipolar disorder, and major depression." (PMID 33888138, 2021). "This study suggests that Gad2, Vamp2, and Pde2a are potentially involved in depression remission treated by Chaihu-Shugan-San." (PMID 35111057, 2021). "A systematic review found that major histocompatibility complex, class I-related gene polymorphisms, and glutamate decarboxylase (GAD) genes (GAD1 and GAD2) contributed to the development of depression." (PMID 31281445, 2019). "The decreased expressions of mRNAs in CUMS-induced depression mice include Slc6a11, Hap1, Gad1, Gad2, Gng4, Slc32a1, Doc2g, Slc32a1, Magel2, Prkcd, Ngfr, Dusp1, Th, Itih3, Cacna2d2, Arc, Mbp, Peg10, Fos, and so on." (PMID 27427907, 2016). "Depression patients had Gad2 antibody positive and Gad2 mRNA expression increased." (PMID 35111057, 2021). "In the Virginia Adult Twin Study of Psychiatric and Substance Use Disorders 14 SNPs from GAD2 were first genotyped in 188 cases with internalizing disorders (major depression, GAD, panic disorder, agoraphobia, social phobia, or neuroticism personality trait) and 188 controls." (PMID 23659354, 2013). "In addition to the reduction in SST in depression, there is also a deficit in expression of the GABA-synthesizing enzymes glutamate decarboxylase 1 (GAD1, also known as GAD67) and GAD2 (also known as GAD65)." (PMID 27660699, 2016). "There are no previous studies on Gad2 expression in FC in depression, but in the cingulate cortex of postmortem human subjects with MDD, a significant reduction in Gad2 expression leading to GABA depletion has been demonstrated." (PMID 25423262, 2014). "Therefore, HF may improve depression symptoms by regulating including but not limited to MAOA, MAOB, AR, CAMK2A, and GAD2." (PMID 34306154, 2021).